PPP1R14B-AS1 (PPP1R14B antisense RNA 1)
Gene: Long non-coding RNA gene on chromosome 11 (64,245,837 to 64,248,276, forward strand). Ensembl gene ENSG00000256940.
Diseases named in the same sentence as PPP1R14B-AS1 in open-access papers:
PPP1R14B-AS1 is named in the same sentence as 2 diseases in open-access papers, as found by Europe PMC text mining. Sharing a sentence is not in itself a finding about the gene and the disease. The quoted sentences say what the papers report.
liver cancer (1 paper, 2021). An epithelial or non-epithelial malignant neoplasm that arises from the liver. "Long noncoding RNA PPP1R14B antisense RNA 1 (PPP1R14B-AS1) has emerged as a critical modulator of liver cancer and lung adenocarcinoma progression." (PMID 37303940, 2021).
PPP1R14B-AS1 also shares sentences with these, for which no sentence is quoted: lung adenocarcinoma (1 paper).